CASP1 (caspase 1)
Diseases named in the same sentence as CASP1 in open-access papers (continued):
Sharing a sentence is not in itself a finding about the gene and the disease.
COVID-19 (continued). "Monocytes isolated from COVID-19 patients have also been found to have increased caspase-1 activation and cell death compared to those from healthy donors, suggesting inflammasome activation and pyroptosis may be involved in COVID-19." (PMID 33499234, 2021). "Melatonin suppressed the lung cytokine storm in COVID-19 patients by reducing CASP1 expression." (PMID 34975885, 2021). "Similarly, inflammasome components, including NLRP3, ASC specks, and caspase-1, are found in leukocytes of post-mortem lung samples of patients with fatal cases of COVID-19." (PMID 34360684, 2021). "Additionally, active intracellular caspase-1 was detected in PBMCs obtained from COVID-19 patients, and the maintenance of these cells in culture resulted in increased active caspase-1 and IL-1β in the supernatant." (PMID 34977191, 2021). "Inhalation of Idelalisib may result in suppression of Caspase-1, IL-1, and IL-6 by blocking PI3Kδ and may therefore have a strong anti-inflammatory effect on COVID-19." (PMID 32973818, 2020). "Furthermore, post-mortem analysis of lung and heart tissue from COVID-19 patients revealed elevated caspase-1 expression, indicating activation of the pyroptotic cell death pathway and suggesting a role for inflammasome-driven inflammation in disease pathology." (PMID 41550884, 2026). "Taken together, we presented that differentially expressed genes: CASP1, CD4, and EIF2AK3 might be considered as the diagnostic biomarker for COVID-19 and characteristic immunological infiltration could influence the systemic immune microenvironment in the pathogenesis of COVID-19." (PMID 37228369, 2023). "Pregnancies complicated by both COVID-19 and preeclampsia, preeclampsia, and COVID-19 significantly had the highest placental damage on apoptotic, pyroptotic, and necrotic pathways shown from caspase-3, caspase-1, and tumor necrosis factor-alpha expressions in the placenta (P<.05)." (PMID 37362630, 2023). "Interestingly, a recent study on caspase-8 suggests, consistently, that caspase-1 might also assist towards the development of therapeutic strategies to treat COVID-19." (PMID 35163769, 2022). "A recent study suggests that endothelial pyroptosis may play a more important role in the pathogenesis of SARS-CoV-2 than A(H1N1)pdm09, as caspase 1 was found to be elevated in lung endothelial cells from tissue samples of COVID-19 patients compared to H1N1 patients and control samples." (PMID 33499234, 2021). "We found that individuals with obesity and COVID-19 exhibited heightened activation of part of the NLRP3 inflammasome pathway, as evidenced by elevated levels of key protein structures such as ASC and CASP-1." (PMID 40004007, 2025). "A statistically significant difference in marker expression in favor of COVID-19 group A was found for ASC (p = 0.0387) and CASP-1 (p = 0.0142)." (PMID 40004007, 2025). "We concluded that COVID-19 activates the NLRP3 inflammasome pathway, possibly leading to pyroptotic cell death mediated by caspase-1." (PMID 40004007, 2025). "In conclusion, MMP9, CASP1, and CAMP were identified as promising biomarkers and potential targets for therapy of post-COVID-19 GBS." (PMID 40433617, 2025). "The RNAseq data on whole blood (EGAS00001004503) of 10 controls, 20 severe and 19 mild COVID-19 patients showed log2 fold change in NLRP3 (1.25), CASP-1 (1.21) and IL-1β (1.38) in severely infected patients only." (PMID 38748756, 2024). "From day 0 to day 7, a significant induction of the inflammasome pathway genes, which included NLRC4, NLRP1, CASP1, PYCARD, and IL-18, was detected in COVID-19+ individuals compared to healthy controls." (PMID 38543837, 2024). "Diacerein-treated COVID-19 patients presented a smaller area under the curve for NLRP3, caspase-1 and GSDM-D measured on days 2, 5, and 10 after hospitalization compared to those receiving a placebo (p < 0.05)." (PMID 39434905, 2024).
COVID-19 (continued). "Compared to percentages of CASP1+ blood monocytes, BAL-derived monocytes/macrophages (HLADR+CD14+/low CD16−/+) showed increased FLICA CASP1 signal from the patients with COVID-19." (PMID 39240187, 2024). "Meanwhile, the correlation analysis of ICD-related DEGs and immune cell infiltration in severe COVID-19 showed that TLR4, PIK3CA, FOXP3, ENTPD1, CD4, CASP1 and BAX were significantly correlated with a variety of immune cell infiltration." (PMID 38600309, 2024). "During COVID-19, strong activation of the NLRP3-inflammasome and caspase-1 is induced with subsequent release of IL-1β and IL-18, although these cytokines remain difficult to detect in patient’s blood." (PMID 39882243, 2024). "Lower inflammasome pathway activation was observed with significantly lower gene and protein expression of NLRP3, cleaved caspase-1, ASC and IL-1β among severe COVID-19 patients treated with VitD3." (PMID 38748756, 2024). "Nonetheless, a significant decrease in plasma levels of key NLRP3 inflammasome markers, specifically NLRP3, caspase-1, and GSDM-D, was observed in COVID-19 patients who received a 10-day diacerein treatment compared to those who received placebo." (PMID 39434905, 2024). "The log2 fold change of differentially expressed genes (DEGs) in monocytes within PBMCs of severe and mild COVID-19 patients confirmed the log2 fold change observed in NLRP3 (0.22), CASP-1 (0.29) and IL-1β (1.16) during severe stages of SARS-CoV-2 infection." (PMID 38748756, 2024). "In the present study of three prospective cohorts of COVID-19-patients, we investigated caspase-1 activation and IL-1 signature using post-mortem lung tissue, bronchoalveolar lavage fluid (BALF), and serum across the spectrum of COVID-19 severity." (PMID 39882243, 2024). "Compared with non-COVID-19 subjects, the expression of NLRP3 and caspase-1 was increased along the vascular wall in COVID-19 ARDS cases, suggesting the activation of NLRP3 inflammasome in vessel wall." (PMID 37251383, 2023). "Taken together, these data indicate that IL-1β, caspase-1, ASC and IL-18 are reliable biomarkers of COVID-19." (PMID 37168848, 2023). "Among them, the expression of CD4 (p < 0.001) in COVID-19 samples was lower than that of control samples, while CASP1 (p = 0.018) and EIF2AK3 (p = 0.012) were higher in COVID-19 samples." (PMID 37228369, 2023). "Placental expressions of caspase-3, caspase-1, and TNF-alpha were significantly high in pregnancies complicated by both COVID-19 and preeclampsia, suggesting highly morbid placental damage with unfavorable perinatal outcomes." (PMID 37362630, 2023). "Since caspase-1-independent pathway also gives rise to enhanced IL-18 secretion, the relationship between NLRP3 inflammasome activation and COVID-19 development is an important subject to be further addressed." (PMID 37251383, 2023). "CD14highCD16- monocytes derived from severe COVID-19 patients showed increased NLRP3 inflammasome activation potential, as shown by the formation of ASC speck/caspase-1 complexes and increased IL-1β secretion." (PMID 37251383, 2023). "NLRP3 assembly with consequent activation of caspase-1 and downstream consequences like increased active TNF-alpha, IL-1beta and IL-18 are increased in the lungs of fatal COVID-19 cases." (PMID 36555204, 2022). "Co-targets were 194 genes intersecting with COVID-19, RA-DEGs (GSE55235), and pyroptosis-related genes, including 7 genes: CASP1, CASP8, IL1B, CASP3, JUN, EGFR, CXCL8." (PMID 36532040, 2022). "Caspase 1 which has been reported to show an increase with ARDS and MV and has recently been found to increase with COVID-19." (PMID 35144622, 2022). "We observed a significant increase in mRNA expression of NLRP3, pro-caspase-1 (CASP1), and pro-IL-1β genes in HMEC-1 cells exposed to exosomes from the plasma of severe COVID-19 patients compared with that from healthy subjects." (PMID 35587188, 2022).
COVID-19 (continued). "Once inflammasome complexes are formed, active caspase-1 cleaves and proteolytically activates the proinflammatory IL1-family cytokines, IL-1β and IL-18, typically elevated and characteristic of severe COVID-19 in patients." (PMID 35483404, 2022). "Upregulated genes in late COVID-19 mortality included those involved in pyroptosis (e.g., GZMA, CASP1) and fibrosis (COL1A1)." (PMID 35446789, 2022). "In peripheral blood immune cells and tissues of COVID-19 patients, activated NLRP3 inflammasome, caspase-1, and high levels of GSDMD-NT were found, as well as elevated expression of IL-1β and IL-18 in serum." (PMID 36532040, 2022). "Our results revealed that exosomes from severe COVID-19 patients trigger (i) NLRP3, caspase-1, and IL-1β transcription; (ii) NLRP3 inflammasome activation; and (iii) maturation and secretion of IL-1β from endothelial cells." (PMID 35587188, 2022). "This latest technology presents the benefit of studying the caspase 1 activation in specific cell types and subpopulations and has been used to investigate the NLRP3 inflammasome activation in COVID-19 patients." (PMID 36291172, 2022). "Lungs from COVID-19 ARDS subjects co-labeled for NLRP3 and caspase 1, showed colocalization (yellow) along the vessel wall." (PMID 35144622, 2022). "The IHC analysis showed increased expression of caspase-1, ICAM-1, IL-1β, IL-6, MMP-9, TNF-α, and other markers in the hearts of COVID-19 patients." (PMID 34804033, 2021). "In addition, according to GO analysis, CASP1 was clustered in the cell death pathway; thus, we speculate that CASP1 has a key role in the programmed cell death of lymphocytes in patients with COVID-19, and this function may be closely related to disease severity." (PMID 34301919, 2021). "However, our findings also suggest that in people with obesity and COVID-19, the predominant inflammatory pathway activated is the NLRP3 inflammasome, probably leading to pyroptotic cell death mediated by caspase-1." (PMID 40004007, 2025). "Additionally, the distribution of the haplotypes of NLRP3, NLRC4, NLRP1, CARD8, CASP1, IL1B, and ATG16L1, with a frequency greater than 5% in HC, were similar between COVID-19 patients with mild, moderate, severe, and critical infection, and HC." (PMID 38612539, 2024). "Thus, we assessed the regulation of the NLRP3 subunit and its downstream effector caspase 1, in the in vitro HPMVEC COVID-19 model." (PMID 38771750, 2024). "Monocytes (HLADR+CD14+/low CD16−/+) showed little to no CASP1+ signal in both COVID-19 and healthy donors." (PMID 39240187, 2024). "Monocytes and macrophages from the BAL fluid, but not from the peripheral blood of COVID-19 patients, displayed caspase-1 cleavage." (PMID 39240187, 2024). "For instance, IL1B, NFKB1, NLRP3, PYCARD, and CASP1 are listed in the COVID-19 Disease Map, while there are molecules absent from it, including CCL3, 3L1, 4L2, CXCL1, 2, 3, 5, 16, TNFAIP6, C15orf48, TMEM176A/B, NFE2, PADI4, RAB20, ETS2, PHLDA2, FOLR3, and HP." (PMID 37719701, 2023). "However, with AUC values above 0.7 for caspase-1 and ASC, our findings indicate that these proteins are also reliable biomarkers of the inflammatory response in COVID-19." (PMID 37168848, 2023). "Opposed potentials of caspase-1 activation were observed between nonclassical monocytes and immature neutrophils from severe/critical COVID-19 patients upon NLRP3 inflammasome stimulation." (PMID 37251383, 2023). "Notably, circulatory exosomes from severe COVID-19 patients were able to increase the expression of NLRP3, caspase-1 and IL-1β in endothelial cells." (PMID 37251383, 2023). "Taken together, these data suggest that even after recovery, caspase-1 and ASC play a role in the chronic inflammatory immune response that might further exacerbate the long-term effects of COVID-19." (PMID 37168848, 2023).
COVID-19 (continued). "As shown in a recent study, activation of the inflammasome in SARS-CoV-2-infected lung-resistant macrophages is the major driver of COVID-19, and the subsequent inhibition of the inflammasome with small molecules targeting NLRP3 or caspase-1 reverses chronic lung pathology." (PMID 35997950, 2022). "The nucleocapsid binds GSDMD and hinders GSDMD processing by caspase-1, therefore these insights into how SARS-CoV-2 antagonizes cellular inflammatory responses may open new perspectives for COVID-19 treatment." (PMID 35336077, 2022). "Peripheral blood mononuclear cells (PBMCs) derived from severely ill COVID-19 patients display elevated expression of highly active NLRP3 inflammasome, as reflected by abundant levels of cleaved caspase-1 as well as mature IL-1β and IL-18 released upon stimulation in vitro." (PMID 36209522, 2022). "It was demonstrated that monocytes in COVID-19 patients are the outposts of SARS-CoV-2 invasion via TLR sensing and can release inflammatory cytokines by assembling NLRP3, activating caspase-1 to generate a “cytokine storm,” and synthesizing GSDMD-NT to induce cellular pyroptosis." (PMID 36532040, 2022). "In a proteomic analysis by mass spectrometry, we did not detect NLRP3, caspase-1, IL-1β, or NF-κB proteins in the COVID-19 patient exosomes." (PMID 35587188, 2022). "In one clinical study, high activity of caspase-1 was detected in CD3+ CD4+ CD45+ T cells and CD3+ CD45+ T cells, and increased levels of lactate dehydrogenase, a marker of pyroptosis, and IL-18 were observed in COVID-19 patients." (PMID 34360684, 2021). "The higher levels of Caspase-1 p20 and IL-18 indicated more severe symptoms and worse prognosis in patients with COVID-19, suggesting that NLRP3 inflammasome is not only activated but also plays a key role in COVID-19 progression." (PMID 34150848, 2021). "Indeed, activation of CASP1 by activating inflammasomes in response to the SARS-CoV-2 infection activates IL1B and IL18 and contributes to hypercytokinemia in COVID-19 patients." (PMID 34975885, 2021). "To determine the biomarker reliability of the inflammasome signaling proteins caspase-1, ASC, IL-1β and IL-18, we plotted ROC curves for each protein using data from healthy subjects and from patients that tested positive for COVID-19 and presented an active infection." (PMID 37168848, 2023). "In addition, the inflammation and necrotic processes were prominently shown by overexpression of caspase-1 and tumor necrosis factor-alpha (TNF-α), which were significantly high in pregnancies complicated by COVID-19 and pregnancies complicated by preeclampsia." (PMID 37362630, 2023). "This study aimed to investigate the roles of caspase-1, caspase-3, and TNF-alpha expressions in the placenta of pregnant women with both preeclampsia and COVID-19, COVID-19, and preeclampsia and to determine whether preeclampsia with COVID-19 damages the placenta." (PMID 37362630, 2023). "We observed that the patients suffering from COVID-19 underwent a process of cell death called pyroptosis, which is dependent on inflammasome activation and shows a very specific caspase expression, relying on CASP1 (but not CASP9)." (PMID 36361818, 2022). "Furthermore, S6 and S7 cells highly expressed pyroptotic genes (such as NLRC4/5, NLRP1/12 and CASP1) in both KD and severe COVID-19 patients (data not shown)." (PMID 36159873, 2022). "Indeed, NLRP3 and caspase 1 expression were not significantly different from COVID-19 lungs." (PMID 35144622, 2022). "While a recent report showed high levels of NLRP3 inflammasome and caspase 1 expression in lungs with fatal COVID, the status of the NLRP3 inflammasome on the pulmonary vascular wall in COVID-19 is not known." (PMID 35144622, 2022).
COVID-19 (continued). "For this, we have measured the expression of the different players implicated in the NLRP3 inflammasome pathway including NLRP3, CASP-1, ASC, IL-1β and IL-18 in whole blood of severe COVID-19 patients treated or not with 50,000 IU cholecalciferol once per week for 2–3 weeks during their stay at ICU." (PMID 38748756, 2024). "Moreover, exosomes from patients with severe COVID-19 (but not light COVID-19 or healthy donors) induced the expression of NLRP3, pro-caspase-1 and pro-IL-1β in human endothelial cells, microvascular endothelial cells and liver endothelial cells." (PMID 38439942, 2023). "When compared to non-infected controls, protein levels of caspase-1, ASC, IL-1β and IL-18 were higher in patients with active (Positive) COVID-19 (median day of blood collection: 11 days) and in patients who recently recovered from COVID-19 (median day of blood collection: 61.5 days)." (PMID 37168848, 2023). "We analyzed the protein levels of the inflammasome signaling proteins caspase-1, ASC, IL-1β and IL-18 in patients with COVID-19 and patients who had recently recovered from a COVID-19 infection and compared them to the levels in plasma samples from healthy donors, who never had COVID-19." (PMID 37168848, 2023).